ELF4 (E74 like ETS transcription factor 4)
Diseases named in the same sentence as ELF4 in open-access papers (continued):
Sharing a sentence is not in itself a finding about the gene and the disease.
enteritis (3 papers, 2022 to 2025). Inflammation of the small intestine. "According to previous literature reports, ELF4 inactivation mutation triggers a high inflammation response, leading to allergic reactions and enteritis in macrophages." (PMID 38022496, 2023). "In a study of a model of enteritis, ELF4 deficiency led to more severe DNA damage in mice in vitro and in vivo, and ELF4 deficiency made host cells more prone to cancer." (PMID 35928113, 2022). "Moreover, both mouse models and patient studies have demonstrated that ELF4 loss of function can lead to enteritis, but the mechanisms underlying ELF4’s protective role in IBD and autoimmune diseases remain largely unknown." (PMID 41300273, 2025). "In conclusion, our study indicates that the expression level of ELF4 was downregulated in the colon tissue of mice with enteritis." (PMID 38022496, 2023). "It is reported that in a mouse model of enteritis, ELF4 regulates the expression of PARP-1 through its involvement in the DDR process, thereby inhibiting its oncogenic effects." (PMID 35928113, 2022).
neuroblastoma (3 papers, 2020 to 2025). Neuroblastoma (NB) is the most common solid, extracranial childhood tumor. "In neuroblastoma, ELF4 facilitates the proliferation of cancer cells by affecting the dimerization partner, RB-like, E2F, and multi-vulval class B (DREAM) complex and maintains an undifferentiated state of the tumor, acting as a target of miR-124." (PMID 40083328, 2025). "For example, high ELF4 expression promotes neuroblastoma proliferation and maintains poorly differentiated phenotype 28." (PMID 36923538, 2023). "In neuroblastoma, miR-124 induces neuroblastoma differentiation by downregulating the expression of the transcription factor ELF4." (PMID 32873299, 2020). "ELF4 is highly expressed in neuroblastoma and is positively correlated with poor patient survival." (PMID 40083328, 2025).
ovarian carcinoma (3 papers, 2014 to 2025). A malignant neoplasm originating from the surface ovarian epithelium. "In contrast, ELF4 promotes the growth properties of ovarian cancer cell lines (SKOV3 cells and CAOV3 cells) and induces the malignant transformation of NIH3T3 cells." (PMID 40083328, 2025). "ELF4 is highly expressed in various cancers, including leukemia, ovarian cancer, liver cancer, papillary thyroid cancer, and nasal NK/T-cell lymphomas." (PMID 40083328, 2025). "ELF4 is highly expressed in ovarian cancer and ovarian cancer cell lines, and cell malignancy declines after knocking down ELF4, suggesting that ELF4 is an oncogene in ovarian cancer." (PMID 41300273, 2025). "MEF (myeloid ELF1-like factor, also known as ELF4) is expressed in a significant proportion of ovarian carcinomas." (PMID 25079112, 2014).
ulcerative colitis (3 papers, 2023 to 2025). An inflammatory bowel disease involving the mucosal surface of the large intestine and rectum. "A previous study found that ELF4 expression is significantly suppressed in colon tissues derived from ulcerative colitis, and that reduced ELF4 leads to susceptibility to colitis-associated cancer." (PMID 36923538, 2023). "Notably, ELF4 was significantly downregulated in the intestinal epithelial tissues of active ulcerative colitis patients and in mouse models." (PMID 41300273, 2025).
viral infections (3 papers, 2018 to 2025). "In vivo experiments have shown that ELF4-deficient mice were more sensitive to virus infection after challenge with a lethal dose of West Nile virus (WNV) compared to WT mice, and the ability of macrophages to produce type I IFNs was damaged." (PMID 41300273, 2025). "An individual with recurrent viral infections and mild hypogammaglobulinemia was identified to have an X-linked damaging variant in the transcription factor gene ELF4." (PMID 36477361, 2022). "We can treat viral diseases by artificially increasing the body’s ELF4 levels to manipulate its IFN levels." (PMID 41300273, 2025). "We now explore the role of ELF4 in miRNA production after viral infection, and its importance in viral pathogenesis and host defense." (PMID 30089112, 2018). "We recently demonstrated that ELF4 is activated by RLR signaling after viral infection." (PMID 30089112, 2018). "Here we revealed a role for ELF4 in miRNA production following viral infection." (PMID 30089112, 2018). "So we attempted to test whether ELF4 might regulate some miRNAs in response to viral infection." (PMID 30089112, 2018).
autoimmune disease (2 papers, 2024 to 2025). A disorder resulting from loss of function or tissue destruction of an organ or multiple organs, arising from humoral or cellular immune responses of the individual to their own tissue constituents. "However, one of the top HOMER results was from the ELF family, which has been associated with autoimmune disease, and the reduction in ELF4 in macrophages has been correlated to increased neutrophilic infiltration." (PMID 39524441, 2024). "The discovery that ELF4 regulates the type I IFN response provides new insight, methods, and perspectives in the development of antiviral and anticancer strategies and treatment of autoimmune disorders induced by IFNs." (PMID 41300273, 2025).
colon cancer (2 papers, 2025). "In a dextran sodium sulfate-induced mouse chronic colitis model, it was unexpectedly found that ELF4 gene-deficient mice were highly susceptible to colitis-associated colon cancer." (PMID 41300273, 2025).
epilepsy (2 papers, 2021 to 2025). A brain disorder characterized by episodes of abnormally increased neuronal discharge resulting in transient episodes of sensory or motor neurological dysfunction, or psychic dysfunction. "It should be noted, however, that the ETS expression profile is also different in epilepsy; ELF1, ELK1, ELK4, ETS1, ETS2, and ETV1 are expressed at higher levels than ELF4, ELK3, and ETV4, and there is also variability in expression among different types of epilepsy." (PMID 33671331, 2021).
esophageal squamous cell carcinoma (2 papers, 2023 to 2025). Esophageal squamous cell carcinoma (ESCC) is a type of esophageal carcinoma (EC) that can affect any part of the esophagus, but is usually located in the upper or middle third. "In esophageal squamous cell carcinoma, ELF4 is associated with poor prognosis and advanced tumor stages." (PMID 40083328, 2025). "Similarly, ELF4 is up-regulated and facilitates the expression of fucosyltransferase 9 (FUT9; encoding a cancer stem-like properties affecter) in esophageal squamous cell carcinoma, thereby enhancing cancer stem-like properties and promoting tumor progression." (PMID 40083328, 2025). "However, the specific role of ELF4 in esophageal squamous cell carcinoma (ESCC) remains unclear." (PMID 37674363, 2023).
liver cancer (2 papers, 2022 to 2025). An epithelial or non-epithelial malignant neoplasm that arises from the liver. "However, tumorigenesis is a complex and multistep process involving various molecules, and the significance of ELF4 fusion in liver cancer occurrence remains to be clarified." (PMID 36158120, 2022).
lymph node metastasis (2 papers, 2020 to 2023). "In both cohorts, elevated ELF4 was positively correlated with worse tumor differentiation, lymph node metastasis, distant metastasis and higher AJCC stages." (PMID 36923538, 2023). "A clonal driver mutation in MYCN (MIM: 164840; CRC-190), and subclonal driver mutations in ELF4 (MIM: 300775; 083-03), PTPRB (MIM: 176882; CRC-233 lymph node metastasis), FUS (MIM: 137070), and ERCC4 (MIM: 133520) in CRC-449 were all specific to metastatic tumours." (PMID 33053768, 2020).
melanoma (2 papers, 2020 to 2025). A malignant, usually aggressive tumor composed of atypical, neoplastic melanocytes. "In melanoma, several ETS TFs, including FLI1, SPI1, ELF4, ETV7, SPIB, and SPIC, are expressed at higher levels in Cluster A patients, whereas ETV5, ETV4, ELK1, ERF, and ETV2 showed increased expression in Cluster B patients." (PMID 41502516, 2025).
pancreatic cancer (2 papers, 2019 to 2023). "Downregulation of ELF4 in pancreatic cancer may enhance the efficacy of oncolytic adenovirus treatment." (PMID 36923538, 2023). "Among them, ELF4 has been found to be expressed during pancreatic development and RLF overexpression has been correlated to poor survival in pancreatic cancer patients strengthening the possibility of their involvement in the pathogenesis of PDAC, which could be explored further." (PMID 31795960, 2019).
Promyelocytic Leukemia (2 papers, 2021 to 2025). "Our hypothesis is supported by previous studies that show that the loss of ELF4 causes a profound abrogation in BCR-ABL associated Chronic Myeloid Leukemia and the direct interaction between the Promyelocytic Leukemia (PML) gene and ELF4." (PMID 33836003, 2021).
Arrhythmia (1 paper, 2024). Any cardiac rhythm other than the normal sinus rhythm. "CL (CCA1/LHY), as a typical early-morning gene, had a halving of its cycle and unstable gene expression when the photocycle became shorter, and EL (ELF4/LUX) had a large arrhythmia." (PMID 39415971, 2024).
autoimmune disorders (1 paper, 2025). "Additionally, the loss-of-function mutation of ELF4 can cause patients to develop symptoms of mucosal autoimmunity and IBD, manifested as low-grade fever and ulcers." (PMID 41300273, 2025).
cholangiocarcinoma (1 paper, 2025). A carcinoma that arises from the intrahepatic biliary tree (intrahepatic cholangiocarcinoma) or from the junction, or adjacent to the junction, of the right and left hepatic ducts (hilar cholangiocarcinoma). "In HuCCT1 cells, the expression of ELF4 is up-regulated and ELF4 is a potential prognostic biomarker for cholangiocarcinoma." (PMID 40083328, 2025).
clear cell renal cell carcinoma (1 paper, 2025). "Similarly, in clear cell renal cell carcinoma (ccRCC), elevated ELF4 levels correlate with worse outcomes, enhancing proliferation, migration, invasion, M2 macrophage polarization, and chemotaxis toward RCC cells." (PMID 41287970, 2025).
esophageal carcinoma (1 paper, 2023). A primary or metastatic malignant neoplasm involving the esophagus. "Additionally, pan-cancer analysis of the expression of ELF4 in TCGA showed that the expression of ELF4 in esophageal carcinoma ranked second and was only lower than that in acute myeloid leukemia tumor." (PMID 37674363, 2023).
fibrosis (1 paper, 2023). the formation of excess fibrous connective tissue in an organ or tissue in a reparative or reactive process. "However, changes in the methylation level of the “driver” genes for oncopathology (АРС, CDKN2B, GSTP1, ELF4, TERT, WT1) are registered in tumor tissue in the setting of liver cirrhosis but not fibrosis." (PMID 36923478, 2023).
Hepatic steatosis (1 paper, 2022). Steatosis is a term used to denote lipid accumulation within hepatocytes. "The hematoxylin and eosin (H&E) staining and Oil red O staining showed that alcohol induced increased hepatic steatosis in Elf4−/− mice compared to WT mice." (PMID 35563234, 2022). "Taken together, the data revealed that Elf4−/− mice showed increased alcohol-induced hepatic steatosis." (PMID 35563234, 2022). "In conclusion, intestinal ELF4 is an important host protective factor in maintaining gut homeostasis and alleviating alcohol exposure-induced hepatic steatosis and injury." (PMID 35563234, 2022). "Thus, we identify ELF4 as an important host protective factor in maintaining gut homeostasis and alleviating alcohol exposure-induced hepatic steatosis and injury, and our study improves the understanding of ALD’s pathogenesis." (PMID 35563234, 2022).
Huntington disease (1 paper, 2024). Huntington disease (HD) is a rare neurodegenerative disorder of the central nervous system characterized by unwanted choreatic movements, behavioral and psychiatric disturbances and dementia. "This includes specific signaling pathways related to mTOR itself, as well as those implicated in Huntington’s disease and the elF4 and p70S6K pathways." (PMID 38927348, 2024).
immunodeficiency disease (1 paper, 2025). Disease in which there is a deficiency or defect in the mechanisms of immunity, either cellular or humoral. "Regarding the crucial roles of ELF4 in immune system development, its mutation results in immunodeficiency diseases." (PMID 40083328, 2025). "The clinical significance of ELF4 in the immune system is underscored by the evidence that the mutation in ELF4 leads to X-linked hypogammaglobulinemia with growth hormone deficiency (XLH-GHD), which is a rare disease caused by immunodeficiency disorder." (PMID 40083328, 2025).
liver disorder (1 paper, 2022). A disease involving the liver. "This indicated more severe liver disorders in the Elf4−/−-EtOH group, compared with the WT-EtOH group." (PMID 35563234, 2022).
lung carcinoma (1 paper, 2023). "On the contrary, ELF4 can inhibit the development of lung cancer and oral carcinoma 30, implying a context-dependent role of ELF4 in cancer." (PMID 36923538, 2023).
lymphoma (1 paper, 2025). A malignant (clonal) proliferation of B- lymphocytes or T- lymphocytes which involves the lymph nodes, bone marrow and/or extranodal sites.
Obesity (1 paper, 2023). Accumulation of substantial excess body fat. "In this study, we constructed a co-expression network between obesity and PTC and identified four common hub genes (MNDA, TNC, CHIT1, MMP9) and two common TFs (ELF4, STAT3), which might provide new diagnostic and therapeutic strategies for obesity-related PTC." (PMID 37671970, 2023). "Further validation revealed that in obesity and PTC, only ELF4 and STAT3 showed high expression levels." (PMID 37671970, 2023).
plasma cell neoplasm (1 paper, 2016). A clonal proliferation of immunoglobulin-secreting plasma cells. "This modelrecapitulates the systemic manifestations of human plasma cell neoplasms, andimplicates cooperativity between the Rad50s andMef/Elf4 pathways in initiating myelomagenic mutations that promote plasma celltransformation." (PMID 26961797, 2016).
tendinitis (1 paper, 2024). Inflammation of a tendon, usually resulting from an overuse injury. "Additionally, our study highlights key molecular pathways, immune cells, and transcription factors involved in tendinitis, such as the roles of MYD88, CD36, CREB5, and ELF4." (PMID 38919626, 2024).
tumor (16 papers, 2010 to 2025). "Here, we found a significant association between the high-ELF4 tumours (Fisher exact test; odds ratio = 6.1, p = 4.5 x 10−47) with high-grade tumours." (PMID 33836003, 2021). "Altogether, we have shown that expression of ELF4 varies across tumours of the 32 cancer types investigated and that there is a link between the expression levels of ELF4 in tumours to the age of patients, the mutation burden, and the clinical outcomes." (PMID 33836003, 2021). "Single-cell RNA sequencing (scRNA)-seq and spatial transcriptome (ST)-seq analyses revealed that ELF4 could induce reprogramming of tumor-associated monocytes/macrophages (TAMMs)." (PMID 39132148, 2024). "Accordingly, compared to the low-ELF4 tumours, we discovered higher gene mutation rates in high-ELF4 tumours, which could explain the poorer outcome exhibited by the patients afflicted with high-ELF4 tumours." (PMID 33836003, 2021). "Put together; we suggest that a combination of factors including the higher-grade tumours, higher mutation burden and the older patient population may in part explain why patients afflicted with high-ELF4 tumours level have worse survival outcomes." (PMID 33836003, 2021). "Analysis of ELF4 in various human cancers has revealed that it plays essential roles in cellular differentiation, proliferation, and apoptosis in cancers of the prostate and breast, and is paradoxically associated with oncogenic activity and tumour suppressor roles." (PMID 33836003, 2021). "Although lots of studies have reported that ELF4 is inhibited or deleted to facilitate tumorigenesis as a tumor suppressor, it also acts pro-oncogenic function in some tumors." (PMID 40083328, 2025). "The circZNF451/FXR1/ELF4/IRF4 axis reshapes the tumor immune microenvironment by inducing the polarization of M2 macrophages, which subsequently inhibits the sensitivity of anti-programmed death-1 (PD-1) therapy in lung adenocarcinoma." (PMID 40083328, 2025). "ELF4 is down-regulated to promote tumor progression in some cancers, while ELF4 is highly expressed in other cancers and facilitates tumorigenesis." (PMID 40083328, 2025). "ELF4 plays a bidirectional role in tumor suppression and tumorigenesis, with its role being dependent on cellular context." (PMID 40083328, 2025). "In past years, it has been demonstrated that ELF4 acts as both a tumor suppressor and an activator in a cell-context manner." (PMID 40083328, 2025). "Specifically, ELF4 plays a critical role in cancer metastasis, proliferation, and modulation of the tumor microenvironment." (PMID 40083328, 2025). "Transcription factor E74, like ETS transcription factor 4 (ELF4), is dysregulated by posttranslational modifications, gene fusions, and complex signaling crosstalk, exhibiting both tumor-suppressing and tumor-promoting effects." (PMID 41440381, 2025). "The correlation of ELF4 expression with endothelial cells and cancer-associated fibroblasts also indicates the potential roles of ELF4 in regulating angiogenesis and tumor extracellular matrix remodeling in the TME." (PMID 40083328, 2025). "This review synopsizes the oncogenic characteristics of ELF4, as a pivotal regulator of both tumor suppression and activation, with a particular emphasis on its roles in tumor invasion, metastasis, proliferation, and immunity." (PMID 40083328, 2025). "In one study, researchers investigated the role of ELF4 and found that it is upregulated in breast cancer cells and leads to tumor growth and metastasis." (PMID 39132148, 2024). "The samples with high ELF4 expression subgroup were characterized by tumor invasive and proliferative phenotypes." (PMID 39132148, 2024). "Since it is virtually impossible to test the primary patients’ tumours that either expressed high or low ELF4 levels to several anti-cancer drugs, we used cancer cell lines to test for any differences in their drug responses." (PMID 33836003, 2021).